VSIG4 (V-set and immunoglobulin domain containing 4)
Diseases named in the same sentence as VSIG4 in open-access papers (continued):
Sharing a sentence is not in itself a finding about the gene and the disease.
COVID-19 (6 papers, 2022 to 2025). A disease caused by infection with severe acute respiratory syndrome coronavirus 2. "Based on its position in gene–term network and its role in several important processes in COVID-19 pathogenesis, we consider VSIG4 to be one of the key genes and a potential biomarker and target for therapeutic intervention." (PMID 40374692, 2025). "Expression dynamics of the 36 blood aging biomarkers in COVID-19 mirrored these trends, with VSIG4 levels declining during acute phases and recovering over time, independent of stage-specific differentially expressed genes." (PMID 40500114, 2025). "The identification of key immune-modulating genes like ISG15, SERPING1, C1QA, C1QB, and VSIG4 opens avenues for therapeutic approaches that aim to modulate the immune response and improve outcomes in severe COVID-19 cases via upregulation of expression of these genes." (PMID 40374692, 2025). "Currently, to our knowledge, no therapies for COVID-19 or other infectious diseases have been developed that specifically target ISG15, SERPING1, or VSIG4 genes." (PMID 40374692, 2025).
rheumatoid arthritis (6 papers, 2019 to 2025). A chronic, systemic autoimmune disorder characterized by inflammation in the synovial membranes and articular surfaces. "In addition to its expression profile, VSIG4 functionality in cancer has been suggested by multiple prognostic studies across multiple cancer types, and recently VSIG4 polymorphism has been linked to susceptibility and functional status in rheumatoid arthritis." (PMID 38892347, 2024). "VSIG4 expression has been detected in the tissues of patients afflicted by rheumatoid arthritis and atherosclerosis (AS), which led to speculation that it could potentially be involved in the pathogenesis of inflammatory diseases." (PMID 40405491, 2025). "According to recent research, VSIG4+ cells have been detected in the tissues of individuals with rheumatoid arthritis, atherosclerosis, and chronic hepatitis B virus infected livers, implying that VSIG4 may serve as a contributing factor to the development of such inflammatory conditions." (PMID 38590525, 2024).
Sepsis (6 papers, 2019 to 2022). Sepsis is defined as life-threatening organ dysfunction caused by a dysregulated host response to infection. "The finding encouraged us to carry out further in-depth study on the pathogenic role of VSIG4-positive peritoneal macrophages in a CLP-induced sepsis model using wild-type and VSIG4-knockout mice." (PMID 34023853, 2021). "Of the ICU Day-3 classifying proteins, ST2, CNTN5, and ITGAV decreased significantly in median level from ICU Day-1 to Day-3 and VSIG4 increased significantly in sepsis patient plasma between Day-1 and Day-3." (PMID 36572854, 2022). "In summary, we have shown for the first time that in the CLP-induced mouse sepsis model, VSIG4-positive peritoneal macrophages actively migrate to the thymus and induce apoptosis in double-positive thymocytes, thereby resulting in thymic atrophy." (PMID 34023853, 2021). "The results support strongly that VSIG4 positive macrophages are responsible for double-positive thymocyte apoptosis and thymic atrophy occurring in the sepsis, via migration from the peritoneal cavity into thymus." (PMID 34023853, 2021). "NOD2 inhibitor NOD-IN-1 and VSIG4-siRNA were used as interventions to further investigate the mechanism of histone H3 on pyroptosis in sepsis." (PMID 32432055, 2020). "Extracellular histone H3, whose stimulation could elevate the expression of NLRP3 and NOD2, caused pyroptosis in sepsis via NOD2 and VSIG4/NLRP3 pathways." (PMID 34868031, 2021). "Extracellular histone H3 induced by LPS could cause pyroptosis during sepsis via NOD2 and VSIG4/NLRP3 pathway." (PMID 34906145, 2021). "Thus, in the early stages of sepsis treatment, the control of the VSIG4 positive macrophages is considered important to prevent thymus damage and to maintain patient immunity for the treatment process or/and to prevent recurrence after a treatment." (PMID 34023853, 2021). "On contrary, VSIG4 was down-regulated in sepsis mice but up-regulated by H3 antibody." (PMID 32432055, 2020). "Thus, this is an important new finding in the field of sepsis, and controlling VSIG4-positive macrophages may be an effective method for preventing and treating immune paralysis by polymicrobial infection." (PMID 34023853, 2021). "However, the role of VSIG4-expressing macrophages in sepsis has not been elucidated." (PMID 34023853, 2021).
Arthritis (5 papers, 2016 to 2025). Inflammation of a joint. "VSIG4 is also locally upregulated within the microenvironments of inflammatory diseases, such as arthritis." (PMID 32856419, 2020). "Vsig4 has been reported to be an interesting target for imaging the progression of arthritis and the macrophages involved." (PMID 31288389, 2019). "The percentage of Vsig4 and F4/80 contained within F4/80 positive cells in ankle sections of CIA mice confirmed that the majority of the Vsig4+ cells are F4/80 positive and the Vsig4 low infiltrating macrophages increases in the late stage of arthritis." (PMID 31288389, 2019). "Here, we further addressed the specificity and assessed the potential for arthritis monitoring using near-infrared fluorescence (NIRF) Cy7-labeled Vsig4 nanobody (Cy7-Nb119)." (PMID 31288389, 2019). "Our studies have confirmed that nanobody targeting Vsig4 constitute a specific tool for non-invasive fluorescence in vivo imaging as a way of assessing inflammation in arthritis models in vivo." (PMID 31288389, 2019). "Nanobody against V-set and Ig domain-containing 4 (Vsig4) on tissue macrophages, such as synovial macrophages, could visualize joint inflammation in multiple experimental arthritis models via single-photon emission computed tomography imaging." (PMID 31288389, 2019). "In previous studies, we have shown that specific probes targeting Vsig4 co-stain a subset of CD86 positive subpopulations in inflamed joints of arthritis mice models and can be used for SPECT/CT molecular imaging to monitor and even predict the development of RA." (PMID 31288389, 2019). "In a previous study, we confirmed that Vsig4-specific nanobody targeting synovial macrophages constitutes a specific tool for non-invasive SPECT/CT imaging as a way of detecting early signs of inflammation and assessing inflammation in multiply arthritis models in vivo." (PMID 31288389, 2019).
breast carcinoma (5 papers, 2020 to 2025). "However, the expression levels of SIRT7 were only significantly negatively correlated with two gene markers in breast cancer-luminal, such as VSIG4 (r = −0.108, p = 1.16e-02) and BDCA-1 (r = −0.114, p = 7.69e-03)." (PMID 32528869, 2020).
hepatocellular carcinoma (5 papers, 2021 to 2025). A malignant tumor that arises from hepatocytes. "VSIG4 has been reported to be downregulated in hepatocellular carcinoma (HCC), and its low expression is linked to a poor prognosis in patients with hepatitis B (HBV)-associated HCC." (PMID 36387195, 2022).
lupus nephritis (5 papers, 2020 to 2025). Glomerulonephritis in the context of systemic lupus erythematosus. "Normalized fluorescence intensity values for the five biomarkers (ALCAM, OPN, TNFRSF1B, VCAM1, and VSIG4) were compared between healthy controls (HCs) and lupus nephritis (LN) patient groups." (PMID 40047601, 2025). "Recently, the upregulation of VSIG4 was reported in kidney diseases, including diabetic kidney disease, lupus nephritis, and immunoglobulin A nephropathy." (PMID 33348749, 2020).
autoimmune disease (4 papers, 2020 to 2025). A disorder resulting from loss of function or tissue destruction of an organ or multiple organs, arising from humoral or cellular immune responses of the individual to their own tissue constituents. "Notably, both HLA-I-specific and HLA-II-specific pGenes included known drug targets for autoimmune diseases, infectious diseases, and cancer such as LAG3, PDCD1, TNF, and ACE2 affected by HLA-I; and IL18, TREM2, VSIG4, and TLR1 by HLA-II." (PMID 39085222, 2024).
diabetic kidney disease (4 papers, 2020 to 2026). Progressive kidney disorder caused by vascular damage to the glomerular capillaries, in patients with diabetes mellitus. "A V-set Ig domain-containing 4 (VSIG4), known for complement receptor, has been involved in the profibrotic pathway in chronic kidney disease including diabetic kidney disease." (PMID 42195288, 2026). "Future studies should be considered to reveal the specific mechanism of VSIG4 in diabetic nephropathy in vivo." (PMID 33348749, 2020). "Considering previous study results on the diabetic kidney disease model together with the present study results, VSIG4 could be an important mediator of kidney injury." (PMID 36836636, 2023). "Bioinformatic analyses have revealed that VSIG4 expression is upregulated in diabetic nephropathy." (PMID 36836636, 2023). "Considering these relationships, VSIG4 may be an important mediator of diabetic nephropathy progression." (PMID 35888119, 2022). "Considering that TGF-β is a key mediator of fibrosis in diabetic nephropathy, VSIG4 could be an important factor in the progression of diabetic nephropathy." (PMID 33348749, 2020). "Moreover, VSIG4 is upregulated in diabetic kidney disease, as indicated by bioinformatics analysis." (PMID 33348749, 2020).
Hypertension (4 papers, 2022 to 2025). The presence of chronic increased pressure in the systemic arterial system. "Researchers have discovered that gut microbial DNA and the immunological checkpoint gene VSIG4 play crucial opposing roles in both healthy aging and the development of hypertension and diabetes associated with aging." (PMID 38590525, 2024). "VSIG4 also has a vital function in promoting “healthy aging” by inhibiting insulin resistance and hypertension, which are often linked to the aging process." (PMID 38590525, 2024). "We focus our discussion on the role of CgA in inflammation, glucose metabolism, hypertension, and mitochondrial health, in the context of aging-related regulation of gut permeability on the spread of bacterial DNA and levels of Vsig4/CRIg." (PMID 36440192, 2022). "In addition, VSIG4 expression was remarkably higher among patients who had a history of hypertension (P < 0.05), cardiogenic diseases (P < 0.05), and palpitations (P < 0.05); smokers (P < 0.05); patients aged >60 years (P < 0.05); females (P < 0.05)." (PMID 36644582, 2023).
lymphoma (4 papers, 2020 to 2025). A malignant (clonal) proliferation of B- lymphocytes or T- lymphocytes which involves the lymph nodes, bone marrow and/or extranodal sites. "used soluble VSIG4 as a surrogate marker of activated macrophages for the diagnosis of patients with Lymphoma-associated haemophagocytic lymphohistiocytosis." (PMID 36544770, 2022). "Our study revealed that in VSIG4-deficiency mice bearing lymphoma, a model widely used in immunotherapy and tumor microenvironment study, the frequency of tumor-infiltrating CD8+ T and NK cells was evidently increased, and neutrophils as well as Tregs were profoundly decreased." (PMID 39920772, 2025). "Recently, elevated levels of circulating VSIG4 have been proposed as a surrogate marker for lymphoma‐associated hemophagocytic lymphohistiocytosis, a syndrome of severe inflammation resulting from the expansion of activated Mφ and lymphocytes that are defective in cytotoxic functions." (PMID 32856419, 2020). "Serum VSIG4 levels were found to be significantly increased in patients with lymphoma and can be used for lymphoma diagnosis." (PMID 35292033, 2022).
multiple myeloma (4 papers, 2017 to 2023). "VSIG4 mRNA expression data from the Multiple Myeloma Genomics Portal (MMGP) were analyzed to validate our results." (PMID 28938542, 2017). "Considering massive alterations in the immune system resulted from ASCT and immune suppression throughout the period of treatment, this data implies the possible contribution of VSIG4 expression in anti-myeloma immunity." (PMID 28938542, 2017).
clear cell renal cell carcinoma (3 papers, 2021 to 2024). "Using western blotting, we found that VSIG4 protein expression levels were higher in clear renal cell carcinoma tissues than in normal tissues." (PMID 33692827, 2021). "In addition, VSIG4 and HLA-E were found to be co-expressed in M2 macrophages in renal clear cell carcinoma, enriched in neutrophil activation, and involved in immune responses." (PMID 39726813, 2024). "In clear cell renal cell carcinoma, VSIG4 is upregulated and indicates a poor prognosis." (PMID 35292033, 2022). "Subsequently, we compared VSIG4 protein expression levels between normal renal tissues and clear renal cell carcinoma and found that VSIG4 protein expression levels in tumors were higher than the normal tissues." (PMID 33692827, 2021).
colorectal cancer (3 papers, 2022 to 2025). A primary or metastatic malignant neoplasm that affects the colon or rectum. "We sought to reveal the correlation between VSIG4 and the polarization of tumour‐associated macrophages (TAMs) and the immune escape of tumour cells in colorectal cancer (CRC)." (PMID 40405491, 2025). "The expression levels of VSIG4, ZNF532, MEIS2, and CXCL13 were downregulated, while CXCL10 was elevated between colorectal cancer and normal tissues." (PMID 36909170, 2023). "Among them, MMP12 was highly expressed in colorectal cancer tissues, while ARMCX2, CEBPA, CXCL13, FABP4, HOXC6, SIGLEC1 and VSIG4 were more expressed in normal tissues than in cancer tissues." (PMID 36544770, 2022).
myocardial infarction (3 papers, 2023 to 2025). Gross necrosis of the myocardium, as a result of interruption of the blood supply to the area, as in coronary thrombosis. "We detected VSIG4 mRNA expression after RNA extraction and found that VSIG4 was significantly more highly expressed on D7 (P<0.05) and significantly less expressed on D14 (P<0.05) after myocardial infarction." (PMID 37153746, 2023). "In the present study, we aimed to first observe the changes in VSIG4 expression at different time points following myocardial infarction." (PMID 37153746, 2023). "To assess the changes in VSIG4 expression in macrophages after myocardial infarction, we screened macrophages by flow cytometry on days (D) 1, 3, 7, and 14 after myocardial infarction." (PMID 37153746, 2023). "Subsequently, immunofluorescence and flow-through cytometry were used to further clarify the expression of VSIG4 in M1 and M2 macrophages after myocardial infarction." (PMID 37153746, 2023). "Our findings enhance our understanding of the functions and mechanisms of action of the immune co-suppressor molecule VSIG4 in bone marrow-derived M2 macrophage-mediated fibrotic repair following myocardial infarction." (PMID 37153746, 2023). "VSIG4 is highly expressed on bone marrow-derived macrophages infiltrating the myocardium in the late post-myocardial infarction period." (PMID 37153746, 2023). "However, VSIG4 expression in M2 macrophages promotes fibrosis after acute myocardial infarction, suggesting its potential as an immunomodulatory therapeutic target." (PMID 40630963, 2025). "In the late post-myocardial infarction phase, VSIG4 increases IL-10 and TGF-β production, which promotes myocardial fibroblast differentiation, migration, and conversion to myofibroblasts in the infarct area, thereby mediating the healing of damaged myocardial tissue." (PMID 37153746, 2023). "Subsequently, the area of myocardial infarction and cardiac function was observed in VSIG4-knockout mice to clarify whether VSIG4 plays a role in tissue fibrosis repair following myocardial infarction." (PMID 37153746, 2023). "Immediately afterwards, a bone marrow transmigration assay was conducted to determine whether cardiac-resident macrophages or bone marrow-derived M2 macrophages expressed VSIG4 while regulating fibrotic repair following myocardial infarction." (PMID 37153746, 2023). "Furthermore, in myocardial infarction models, a hypoxic milieu induces M2-like macrophages to express V-set and Immunoglobulin Domain Containing 4 (VSIG4), consequently facilitating the transformation of cardiac fibroblasts into myofibroblasts and leading to cardiac fibrosis." (PMID 41459510, 2025). "The results showed that BMD remarkably decreased the number of VSIG4+CD206+ macrophages that infiltrated the myocardial infarction area after AMI, whereas BMT restored VSIG4 expression and the infiltration of VSIG4+CD206+ macrophages after AMI." (PMID 37153746, 2023). "This indicates that VSIG4 gene deletion does not lead to changes in infiltration of M1 and M2 macrophages after myocardial infarction." (PMID 37153746, 2023).
pancreatic cancer (3 papers, 2023 to 2025). "In our study, we found targeting VSIG4+ TAMs by VSIG4 deficiency or blockade remarkably limited tumor growth and metastasis, especially those derived from anaplastic thyroid cancer (ATC) and pancreatic cancer, two extremely aggressive types." (PMID 39920772, 2025). "Anti-VSIG4 treatment significantly inhibited tumor growth and reduced the tumor weight in pancreatic cancer." (PMID 39920772, 2025). "A previous report showed that knockdown of VSIG4 in human pancreatic cancer cells attenuated tumor growth and metastasis in vivo, while the immune microenvironment was missed due to the disadvantage of the nude mouse xenograft model." (PMID 39920772, 2025). "Subsequently, we examined the effect of anti-VSIG4 therapy on the proportion of immune cells in the pancreatic tumor models." (PMID 39920772, 2025). "Both mRNA and protein expression levels of VSIG4 in two pancreatic cancer cell lines were significantly decreased." (PMID 37097516, 2023). "VSIG4 knockdown impaired the proliferation and migration ability of pancreatic cancer cells both in vitro and in vivo." (PMID 37097516, 2023). "In aggressive cancers (such as undifferentiated thyroid and pancreatic cancer), VSIG4-positive TAMS (VSIG4+ TAMs) regulate SPP1 through Kla modification, promoting neutrophil infiltration and impairing antigen-specific immunity, forming an immunosuppressive TME." (PMID 41181157, 2025). "Also, epithelial mesenchymal transition (EMT) markers were also detected, indicating that VSIG4 contributes to EMT process in pancreatic tumor cells." (PMID 37097516, 2023). "Among them, VSIG4 is evidently highly expressed in PDAC, which is the most prevalent primary pancreatic cancer, than normal pancreas." (PMID 37097516, 2023). "As high expression of VSIG4 was validated in PDAC tissue and negatively correlated with PDAC patients’ prognosis, we then intended to explore its biological function in pancreatic cancer cells." (PMID 37097516, 2023).
preeclampsia (3 papers, 2013 to 2020). Preeclampsia is a hypertensive disorder of pregnancy that is characterized by new-onset hypertension with proteinuria presenting after 20 weeks of gestation, and depending on mild or severe forms may initially present with severe headache, visual disturbances, and hyperreflexia. "Among these genes, we identified VSIG4 as a potential diagnostic marker of severe preeclampsia." (PMID 24349325, 2013). "VSIG4 is known as a potential biomarker of severe preeclampsia." (PMID 28559893, 2017).